GRIN2D (glutamate ionotropic receptor NMDA type subunit 2D)
Diseases named in the same sentence as GRIN2D in open-access papers (continued):
Sharing a sentence is not in itself a finding about the gene and the disease.
autism (2 papers, 2018 to 2026). Persistent deficits in social interaction and communication and interaction as well as a markedly restricted repertoire of activity and interest as well as repetitive patterns of behavior. "Notably, these included transcripts for adhesion proteins such as CDH13, CDH9, CDH15 and SLITRKs, all strongly linked to ASD, presynaptic molecules such as SYNIII and SV2C, associated with non-syndromic autism and SCZ, and post-synaptic transcripts such as DLGAP2 and GRIN2D, linked to SCZ." (PMID 30185603, 2018).
colon cancer (2 papers, 2016 to 2023). "The fact that GRIN2D is expressed to a greater extent in cancerous tissues and in colon cancer in particular, is encouraging in that it suggests a potential for vessel specific targeting, but normal tissue expression would necessitate careful monitoring for tissue toxicity." (PMID 26943033, 2016).
gastric cancer (2 papers, 2025). A primary or metastatic malignant neoplasm involving the stomach. "The highly expressed circRNA BIRC 6 (circBIRC 6) in gastric cancer (GC) patients can increase Cav-1 expression by regulating the miR-488-glutamate ionotropic receptor N-methyl-D-aspartate type subunit 2D (GRIN2D) axis, thereby inhibiting autophagy and promoting GC progression." (PMID 41030451, 2025). "Therefore, the circBIRC6/miR-488/GRIN2D axis promoted CAV1 expression in gastric cancer cells, leading to reduced autophagy." (PMID 40936702, 2025).
hepatocellular carcinoma (2 papers, 2023). A malignant tumor that arises from hepatocytes. "Encoding a subunit of the N-methyl D-aspartate receptor, GRIN2D is highly expressed in hepatocellular cancer and can exert an obstacle effect on the immune response, thus promoting tumor growth." (PMID 38022687, 2023).
status epilepticus (2 papers, 2021 to 2022). Status epilepticus is defined as a continuous seizure lasting more than 30 min, or two or more seizures without full recovery of consciousness between any of them. "Human evidence that ketamine can act on this subunit comes from a case report investigating a mutation in GRIN2D in a child with refractory status epilepticus reporting a dramatic electrical and clinical improvement upon treatment with ketamine." (PMID 35013133, 2022).
cocaine addiction (1 paper, 2022). "There were 13 genes enriched in cocaine addiction and the circadian entrainment signaling pathway (Bdnf, Gnai1, Gnai3, Grin2d, Grm2, Maob, Cam2, Camk2g, Gng12, Mapk1, Pcb4, Prkm2, and Pdyn)." (PMID 36164400, 2022).
convulsion (1 paper, 2023). A rapid and repeated body muscle contract that results in an uncontrolled shaking of the body. "On the other hand, variations in GRIN2D, encoding NMDA2DRs, mainly cause DEE with a variety of convulsions." (PMID 38003469, 2023).
keloid (1 paper, 2025). An irregularly shaped, elevated mark on the skin caused by deposits of excessive amounts of collagen during wound healing. "This work therefore implicated the glutamine–glutamate–GRIN2D axis as an important contributor to keloid progression and highlights it as a potential metabolic and signaling target for therapeutic intervention." (PMID 41562114, 2025). "Thus, our work implicated the glutamine–glutamate–GRIN2D axis as a key contributor to keloid progression and highlights it as a promising metabolic and signaling target for therapeutic intervention." (PMID 41562114, 2025). "This elevation correlates with alterations in glutamate metabolism, suggesting a potential role for GRIN2D in the pathogenesis of keloids." (PMID 41562114, 2025). "RNA-seq data revealed that GRIN2D was significantly upregulated in keloids compared to healthy controls, with other receptors like GRIA1 and GRID1 also showing notable expression changes." (PMID 41562114, 2025). "Transcriptomic analysis revealed significant enrichment of the neuroactive ligand-receptor interaction pathway in keloid tissue, with marked upregulation of the glutamate receptor subunit GRIN2D." (PMID 41562114, 2025). "Overall, these findings indicate that the expression of glutamate receptors, particularly GRIN2D, is markedly elevated in keloid tissues." (PMID 41562114, 2025). "In this study, we identified a marked upregulation of the glutamate receptor subunit GRIN2D in fibroblasts residing within keloid tissue." (PMID 41562114, 2025). "Immunohistochemical staining of GRIN2D shown that the keloid samples exhibit stronger staining intensity compared to controls, confirming the elevated expression of this receptor in keloid tissue." (PMID 41562114, 2025). "In this study, we demonstrated a pronounced upregulation of the glutamate receptor subunit GRIN2D in fibroblasts within keloid tissue, accompanied by enhanced glutamine–glutamate metabolism." (PMID 41562114, 2025). "Furthermore, the neuroactive ligand-receptor interaction pathway exhibited substantial changes, with 31 genes, including GRIN2D, HTR7, and CCKAR were upregulated and 44 genes downregulated in keloid tissues compared to normal skin controls." (PMID 41562114, 2025). "Additionally, 14 genes such as GRIN2D, HTR7, and CCKAR were found to be upregulated in the calcium signaling pathway, while 43 genes, including ATP2A1, ADCY8, and MCOLN3, were significantly downregulated, suggesting that calcium signaling plays a critical role in the pathology of keloids." (PMID 41562114, 2025).
liver cancer (1 paper, 2022). An epithelial or non-epithelial malignant neoplasm that arises from the liver. "Our study suggested that GRIN2D is clinically significant and holds a biological value in liver cancer." (PMID 35646712, 2022). "CHRNE, GFRA2, GFRA3, and GRIN2D may serve as potential biomarker for liver cancer prognosis or immune response." (PMID 35646712, 2022).
mental disorder (1 paper, 2019). A disease that has its basis in the disruption of mental process. "Using knockout-first strains for the GRIN2C and GRIN2D produced on pure C57BL/6N strain, we compared the effect of partial or complete ablation of GluN2C and GluN2D subunit on various behaviors relevant to mental disorders." (PMID 31110197, 2019).
metastatic tumors (1 paper, 2023). "Notably, GRIN2D expression was higher in metastatic tumors than in primary tumors based on analysis from HCMED database." (PMID 37553583, 2023). "Notably, HMGA2 and IL20RB were more highly expressed in metastatic tumors than in primary tumors, consistent with the trend observed for GRIN2D expression." (PMID 37553583, 2023). "We found that GRIN2D was overexpressed in PDAC primary tumor and even higher in metastatic tumor, which is consistently observed using PDAC tumors from HCMDB database." (PMID 37553583, 2023).
cancer (16 papers, 2013 to 2025). A tumor composed of atypical neoplastic, often pleomorphic cells that invade other tissues. "GRIN2D, which encodes the GluN2D subunit of N-methyl-D-aspartate receptors (NMDARs), has been identified as a potential oncogene and a novel therapeutic target in certain types of cancer." (PMID 40535770, 2025). "Several top-ranking IP genes were found in multiple cancer types, including ACCN2, GRIN2D, and TRPV3 that associated with poor prognosis in six cancer types, and P2RX6 in seven cancer types." (PMID 38177502, 2024). "Although many RNA sequencing datasets in public databases indicated that GRIN2D was aberrantly expressed in cancers, its specific role in promoting cancer progression remained unclear." (PMID 37553583, 2023). "GRIN2D, which has been deemed to be a possible oncogene in pan‐cancer, showed a significant increase in gastric lesions." (PMID 32207854, 2020). "This investigation identified GRIN2D alone as having sufficient cancer enrichment and expression, to be taken forward for further investigation." (PMID 26943033, 2016). "Furthermore, pan-cancer analysis using The Cancer Genome Atlas (TCGA) datasets revealed that GRIN2D was upregulated in multiple cancers." (PMID 37553583, 2023). "Therefore, the fact that the effect of radiotherapy reacted in the same direction in our study suggests that especially the treatment methods applied have potential effects to stop the vital functions of cancer cells by suppressing Grin2d, which is involved in calcium metabolism." (PMID 40579643, 2025). "Thus, our study was the first to identify the role of GRIN2D in cancer progression at deeper level." (PMID 37553583, 2023). "Besides, GRIN2D can be used as a critical hub of dysregulated signaling pathways in cancer." (PMID 35295962, 2022). "We concluded that GRIN2D exerted an immunomodulatory role on the tumor microenvironment via NMDA targeting and consequently influence cancer proliferation and metastasis." (PMID 35646712, 2022). "The Grin2d gene, a subunit of this class, is highly expressed in many non-neuron cancer types such as colorectal, pancreas, and lung." (PMID 40579643, 2025).
tumor (12 papers, 2016 to 2026). "Consistent with previous reports, our results identified a transcription factor variant in GRIN2D (rs76754767) as a risk factor for HCC tumour progression." (PMID 40535770, 2025). "The results demonstrated a preferential expression pattern of GRIN1 and GRIN2D (the encoding genes of NMDAR) in tumor cells, highlighting the tumor-specific properties of sarcosine." (PMID 40275333, 2025). "In vivo analysis showed GRIN2D vaccination to be an effective approach to inhibit both physiological and tumour-associated angiogenesis." (PMID 26943033, 2016). "Six hits in five genes [AK3 (rs378117), TRPM3 (rs1329774 and rs4745058), CDH4 (rs2427043), LINC00504 (rs76228864), and GRIN2D (rs76754767)] were associated with a risk of tumour progression, whereas variants in HPGD (rs45593131) and RC3H2 (rs2792999) were suggested as protective factors." (PMID 40535770, 2025). "GRIN2D enhances glycolysis in cancer cells, promoting cell invasion and migration, which consequently contributes to the malignancy of tumor cells." (PMID 40747121, 2025). "Taken together, our results suggest that GRIN2D plays a crucial role in promoting PDAC tumor growth and liver metastasis." (PMID 37553583, 2023). "We also analyzed publicly available datasets (GSE16515 and GSE15471) and found that GRIN2D was significantly upregulated in PDAC tumor tissues compared to non-tumor tissues." (PMID 37553583, 2023). "GRIN2D was identified as the only one subunit in NMDAR gene family which highly upregulated in primary tumor tissue than the normal tissues in both of GEO datasets GSE15471 and GSE16515." (PMID 37553583, 2023). "The utility of immunologically targeting GRIN2D in CRC was demonstrated by the vaccination approach inhibiting murine CRC tumour growth and vascularisation." (PMID 26943033, 2016). "Multiple links have been described between glutamate receptor function and tumour biology, with knockdown of some non-GRIN2D glutamate receptor subunits resulting in both pro and anti-tumour effects." (PMID 26943033, 2016). "Tumours grown in mice vaccinated against GRIN2D were found to display a significant decrease in tumour growth by calliper measurement (p=0.004, Mann-Whitney)." (PMID 26943033, 2016). "Multi-organ tissue array analysis identified GRIN2D to be predominantly expressed in tumour tissue, particularly in colorectal malignancies, where its expression was shown to be associated with increased survival." (PMID 26943033, 2016). "This involved staining 10 samples each of 12 different tumour and matched healthy tissue sample for GRIN2D." (PMID 26943033, 2016). "The resulting surge in glycolytic activity, prompted by BHLHE40 and GRIN2D, not only sustains tumor cell survival and proliferation but also correlates with poor histological differentiation and more aggressive tumor phenotypes, thus contributing to the overall malignancy of GC." (PMID 41171531, 2026). "Our results indicate that miR-129-1-3p was illustrated to serve as a tumor repressor via targeting GRIN2D in TNBC cells and highlight that the restoration of miR-129-1-3p might be a new treatment target for TNBC." (PMID 35295962, 2022). "Additionally GRIN2D IHC staining was assessed by multi-organ tissue array analysis, in order to determine its global tumour and healthy tissue expression profile." (PMID 26943033, 2016). "Consequently, upregulated GRIN2D could effectively promote tumour growth and liver metastasis by activating subcellular signalling pathways and transcription factors." (PMID 40535770, 2025). "Overexpression of GRIN2D in PANC1 cell could promote tumor growth." (PMID 37553583, 2023). "The upregulated GRIN2D could effectively promote tumor growth and liver metastasis in PDAC." (PMID 37553583, 2023). "Knockdown of GRIN2D could significantly inhibit tumor growth and tumor mass." (PMID 37553583, 2023).
tumor (continued). "Our study demonstrated that the upregulated expression of GRIN2D in PDAC cells and tumor tissues played a significant role in cell proliferation, migration, invasion and metastasis both in vitro and in vivo." (PMID 37553583, 2023). "To investigate the expression of GRIN2D in PDAC cells, we performed western blot first and found it was overexpressed in several PDAC cell lines compared to non-tumor cell HPDE." (PMID 37553583, 2023). "To examine the GRIN2D expression in PDAC patients, we performed immunohistochemical (IHC) staining on primary tumors and adjacent non-tumor tissues from 72 PDAC patients." (PMID 37553583, 2023). "By examining their expression in Xenabrowser, we found that HMGA2 and IL20RB were positively correlated with GRIN2D expression and highly expressed in PDAC tumor tissues." (PMID 37553583, 2023). "In order to investigate the functional role GRIN2D plays in tumour endothelium, human umbilical cord vein endothelial cells (HUVEC) were transfected with small interfering RNA (siRNA) duplexes corresponding to GRIN2D, to selectively silence its expression." (PMID 26943033, 2016). "We validated that GRIN2D was overexpressed in PDAC cells and tumor tissues." (PMID 37553583, 2023). "We observed that GRIN2D expression was increased in the ducts and blood vessels of tumor tissues compared to adjacent non-tumor tissues." (PMID 37553583, 2023). "The survival of patients with tumours positive or negative for GRIN2D staining was compared by log-ranks statistical analysis." (PMID 26943033, 2016). "Also, inhibition of GRIN2D can attenuate the tumor progression of Triple- Negative Breast Cancer (TNBC)." (PMID 37553583, 2023).
psychiatric disorder (4 papers, 2013 to 2020). A disorder characterized by behavioral and/or psychological abnormalities, often accompanied by physical symptoms. "PRKCE interacts with several proteins encoded by genes of potential relevance to psychiatric disorders, including the glutamate decarboxylases (GAD1, GAD2), NMDA receptors (GRIN2D, GRIN1), and a metabotropic glutamate receptor (GRM5)." (PMID 23922650, 2013).
cardiovascular disease (2 papers, 2020 to 2024). "The results revealed that miR‐129‐1‐3p, which is a potential biomarker of cardiovascular disease, is highly conserved across species and potentially targets GRIN2D (also known as NMDAR2D, NR2D or GluN2D)." (PMID 31957170, 2020).
GRIN2D also shares sentences with these, for which no sentence is quoted: Anxiety (6 papers); Cognitive impairment (4); memory impairment (3); autism spectrum disorder (2); Cerebral ischemia (2); glaucoma (2); neuroblastoma (2); neurodevelopmental disorder (2); Obesity (2); psychosis (2); Stroke (2); Aphasia (1); Ataxia (1); cholangiocarcinoma (1); Chorea (1); Coffin-Siris syndrome (1); colorectal tumours (1); developmental delay (1); diabetic retinopathy (1); Dystonia (1); encephalopathies (1); Hepatitis B (1); infantile epileptic encephalopathy (1); ischemia (1); ischemic stroke (1); Landau-Kleffner syndrome (1); lung carcinoma (1); melanoma (1); movement disorder (1); neurodegenerative disease (1).
A further 13 diseases each share a sentence with GRIN2D in 1 paper.